ARGLU1 (arginine and glutamate rich 1)
Description:
Dual function regulator of gene expression; regulator of transcription and modulator of alternative splicing. General coactivator of nuclear receptor-induced gene expression, including genes activated by the glucocorticoid receptor NR3C1. Binds to a subset of pre-mRNAs and to components of the spliceosome machinery to directly modulate basal alternative splicing; involved in simple and complex cassette exon splicing events. Binds its own pre-mRNA and regulates its alternative splicing and degradation; one of the alternatively spliced products is a stable intronic sequence RNA (sisRNA) that binds the protein to regulate its ability to affect splicing. Binding of the sisRNA stimulates phase separation and localization to nuclear speckles, which may contribute to activation of nuclear receptor-induced gene expression. May also indirectly modulate alternative splicing. Regulates transcription of genes involved in heart development, neuronal cell function, protein localization and chromatin localization (By similarity). Regulates splicing of genes involved in neurogenesis and chromatin organization (By similarity). Essential for central nervous system development (By similarity). Required for the estrogen-dependent expression of ESR1 target genes. Can act in cooperation with MED1.
Synonyms: FLJ10154
Tractability: PROTAC: ubiquitination databases record sites on it; its protein half-life has been measured.
Gene: Protein-coding gene on chromosome 13 (106,541,673 to 106,568,161, reverse strand). Ensembl gene ENSG00000134884.
Subcellular location: Nucleus; Nucleus speckle; Chromosome
Subcellular location (Human Protein Atlas): Nucleoplasm; Cytosol; Mitochondria
Gene Ontology:
Molecular function: cadherin binding; pre-mRNA binding; protein binding; transcription coactivator activity
Biological process: regulation of alternative mRNA splicing, via spliceosome; positive regulation of DNA-templated transcription
Cellular component: chromosome; nuclear speck; nucleoplasm; nucleus; mitochondrion
Genetic constraint (gnomAD): Loss-of-function variants: 8 observed, 36.47 expected, observed/expected ratio (o/e) 0.22, 90% interval 0.13 to 0.4. The upper end of that interval is the gene's LOEUF score, 0.4, which puts it in group 1 of 6, group 1 being the genes least tolerant of losing a copy. Missense variants: 211 observed, 373.9 expected, observed/expected ratio (o/e) 0.56, 90% interval 0.5 to 0.63. Synonymous variants: 166 observed, 144.07 expected, observed/expected ratio (o/e) 1.15, 90% interval 1.01 to 1.31.
Homologues: Orthologues: chimpanzee ARGLU1 (100% identical), macaque ARGLU1 (100% identical), mouse Arglu1 (98% identical), rat Arglu1 (98% identical), pig ARGLU1 (98% identical), tropical clawed frog arglu1 (91% identical), zebrafish arglu1b (85% identical), Drosophila melanogaster Arglu1 (51% identical).
Diseases named in the same sentence as ARGLU1 in open-access papers:
ARGLU1 is named in the same sentence as 18 diseases in open-access papers, as found by Europe PMC text mining. Sharing a sentence is not in itself a finding about the gene and the disease. The quoted sentences say what the papers report.
breast carcinoma (2 papers, 2020 to 2023). "ARGLU1 acts in cooperation with MED1 (Mediator Complex Subunit 1) and is required for estrogen-dependent gene transcription and breast cancer cell growth." (PMID 32884031, 2020).
neuroblastoma (2 papers, 2019 to 2023). Neuroblastoma (NB) is the most common solid, extracranial childhood tumor. "To verify the roles of ARGLU1 in development and regulation of AS in neurons, we performed rescue experiments by transfection of Arglu1 KO Neuro-2a (N2a) cells, a mouse neuroblastoma cell line, with plasmids containing the full-length Arglu1 cDNA." (PMID 37612280, 2023). "In light of the high expression of Arglu1 in the CNS, we proceeded to characterize the role of ARGLU1 in mouse neuroblastoma Neuro-2a (N2a) cells, which have been used widely to investigate roles of regulatory factors in neural transcription and AS." (PMID 30698747, 2019).
adenovirus infection (1 paper, 2025). "To explore the role of ARGLU1 during adenovirus infection, we examined its impact on viral replication using phenotypically wild-type HAdV5 dl309 in HT and HT-A cells and similarly a deletion mutant, dl1102, that expresses E1A deficient for ARGLU1 binding." (PMID 41186411, 2025).
amyotrophic lateral sclerosis (1 paper, 2023). Amyotrophic lateral sclerosis (ALS) is a neurodegenerative disease characterized by progressive muscular paralysis reflecting degeneration of motor neurons in the primary motor cortex, corticospinal tracts, brainstem and spinal cord. "Recently, Arglu1 was identified as a potential diagnostic gene in amyotrophic lateral sclerosis (ALS), suggesting that ARGLU1 might serve as an anti-apoptotic factor in the adult central nervous system in the context of neurodegenerative diseases." (PMID 37612280, 2023).
anorectal malformation (1 paper, 2017). "In previous cytogenetic studies, two large 13q de novo deletions (9 Mb and 28 Mb in size) involving both ARGLU1 and EFNB2 were reported in patients with mild anorectal malformations and EFNB2 was proposed as a good candidate disease gene." (PMID 28934986, 2017).
epilepsy (1 paper, 2023). A brain disorder characterized by episodes of abnormally increased neuronal discharge resulting in transient episodes of sensory or motor neurological dysfunction, or psychic dysfunction. "Human patients with mutations in Arglu1 display developmental delay and intellectual disability, in some cases concurrent with neurological disorders such as epilepsy and autistic spectrum." (PMID 37612280, 2023). "Haploinsufficient mutation in arginine and glutamine-rich protein 1 (Arglu1), a newly identified pre-mRNA splicing regulator, may be linked to neural developmental disorders associated with mental retardation and epilepsy in human patients, but the underlying causes remain elusive." (PMID 37612280, 2023).
gastric cancer (1 paper, 2022). A primary or metastatic malignant neoplasm involving the stomach. "ARGLU1 down-regulation is in relation to advanced TNM staging as well as more dismal OS of gastric cancer patients." (PMID 35265669, 2022). "Additionally, overexpressed ARGLU1 reduces gastric cancer progression." (PMID 35265669, 2022).
Hypertension (1 paper, 2022). The presence of chronic increased pressure in the systemic arterial system. "Intergenic CpGs cg18264657 and cg11710912 annotated to the ARGLU1 gene that were previously associated with hypertension in other study populations of European and South Asian ancestry were associated with renin concentration and ARR in our Ghanaian study population." (PMID 36457109, 2022).
microcephaly (1 paper, 2023). A congenital or acquired developmental disorder in which the circumference of the head is smaller than normal for the person's age and sex.
Oculomotor apraxia (1 paper, 2017). Ocular motor apraxia is a deficiency in voluntary, horizontal, lateral, fast eye movements (saccades) with retention of slow pursuit movements. "In addition, clinical evaluation of Pt.1 with a de novo 1 Mb deletion revealed developmental regression and ASD, whereas features of Pt.3 who carries a LOF point mutation in ARGLU1 included abnormal movement, cerebellar hypoplasia, and oculomotor apraxia." (PMID 28934986, 2017).
prostate carcinoma (1 paper, 2022). A carcinoma that arises from epithelial cells of the prostate gland. "Considering the influence of ageing on the heterogeneity of prostate cancer as well as clinical prognosis, an ageing-derived gene signature comprised of ARGLU1, EIF2S2, and AP000844.2 was conducted based on WGNCA, random forest, and uni- and multivariate cox regression models." (PMID 35265669, 2022). "Among EIF2S2, ARGLU1, and AP000844.2, at present, there is still a lack of experimental evidence to confirm the role of EIF2S2 in prostate cancer." (PMID 35265669, 2022).
viral infection (1 paper, 2025). "Collectively, these results demonstrate that during viral infection, the sub-nuclear distribution of ARGLU1 is altered." (PMID 41186411, 2025). "Our study identified ARGLU1 as a direct binding partner of HAdV5 E1A that is re-localized in the nucleus during viral infection, regardless of E1A binding, while providing further mechanistic insights into how ARGLU1 enhances cellular stress response." (PMID 41186411, 2025).
tumor (2 papers, 2019). "Similarly, ARGLU1 and CIRBP were lower expressed in tumor compared to metastatic tissue, while QKI was higher expressed." (PMID 30940821, 2019).
cancer (1 paper, 2025). A tumor composed of atypical neoplastic, often pleomorphic cells that invade other tissues. "We have previously demonstrated that ARGLU1 overexpression enhances DDR and increases cancer cell resistance to genotoxic drugs." (PMID 41186411, 2025).
infection (1 paper, 2025). The state of being infected such as from the introduction of a foreign agent such as serum, vaccine, antigenic substance or organism. "Together, these results demonstrate that ARGLU1 is a negative regulator of viral gene and protein expression during infection." (PMID 41186411, 2025). "Furthermore, we demonstrate that during infection, ARGLU1 sub-nuclear distribution is altered into distinct phenotypes not observed in uninfected cells." (PMID 41186411, 2025). "We therefore investigated whether the binding of ARGLU1 by E1A during HAdV5 infection affects DDR." (PMID 41186411, 2025). "Conversely, dl1102 was minimally, and not significantly, affected in growth by ARGLU1 overexpression at 48 and 72 h after infection." (PMID 41186411, 2025).
neurological diseases (1 paper, 2023). "Therefore, establishing an Arglu1 knockout mouse model is crucial to demonstrate an association between Arglu1 and cortical development as well as related neurological diseases." (PMID 37612280, 2023).
ARGLU1 also shares sentences with these, for which no sentence is quoted: neurodegenerative disease (1 paper); Uterine leiomyoma (1).